ENTPD5 (ectonucleoside triphosphate diphosphohydrolase 5 (inactive))
Description:
Hydrolyzes nucleoside diphosphates with a preference for GDP, IDP and UDP compared to ADP and CDP. In the lumen of the endoplasmic reticulum, hydrolyzes UDP that acts as an end-product feedback inhibitor of the UDP-Glc:glycoprotein glucosyltransferases. UMP can be transported back by an UDP-sugar antiporter to the cytosol where it is consumed to regenerate UDP-glucose. Therefore, it positively regulates protein reglucosylation by clearing UDP from the ER lumen and by promoting the regeneration of UDP-glucose. Protein reglucosylation is essential to proper glycoprotein folding and quality control in the ER (By similarity).
Synonyms: CD39L4; PCPH; NTPDase-5
Tractability: Antibody: UniProt places it where antibodies can reach, with high confidence; its Gene Ontology location is reachable by antibodies, with high confidence; UniProt predicts a signal peptide or a membrane-spanning region. PROTAC: its protein half-life has been measured; a small molecule that binds it is known.
Target class: Enzyme; Hydrolase
Gene: Protein-coding gene on chromosome 14 (73,958,010 to 74,019,399, reverse strand). Ensembl gene ENSG00000187097.
Subcellular location: Endoplasmic reticulum; Secreted
Pathways (Reactome):
Disease: Purinergic signaling in leishmaniasis infection
Metabolism: Phosphate bond hydrolysis by NTPDase proteins
Gene Ontology:
Molecular function: ADP phosphatase activity; CDP phosphatase activity; GDP phosphatase activity; IDP phosphatase activity; nucleoside diphosphate phosphatase activity; protein binding; UDP phosphatase activity; hydrolase activity
Biological process: 'de novo' post-translational protein folding; protein N-linked glycosylation; UDP catabolic process; UDP-alpha-D-glucose metabolic process
Cellular component: extracellular region; endoplasmic reticulum
Genetic constraint (gnomAD): Loss-of-function variants: 33 observed, 46.69 expected, observed/expected ratio (o/e) 0.71, 90% interval 0.54 to 0.94. The upper end of that interval is the gene's LOEUF score, 0.94, which puts it in group 4 of 6, group 1 being the genes least tolerant of losing a copy. Missense variants: 440 observed, 487.77 expected, observed/expected ratio (o/e) 0.9, 90% interval 0.83 to 0.98. Synonymous variants: 174 observed, 181.74 expected, observed/expected ratio (o/e) 0.96, 90% interval 0.85 to 1.09.
Homologues: Orthologues: chimpanzee ENTPD5 (99% identical), dog ENTPD5 (93% identical), guinea pig ENTPD5 (90% identical), mouse Entpd5 (88% identical), pig ENTPD5 (88% identical), rat Entpd5 (86% identical), zebrafish entpd5a (55% identical), tropical clawed frog entpd5 (54% identical), zebrafish entpd5b (54% identical), Drosophila melanogaster NTPase (38% identical), Caenorhabditis elegans uda-1 (35% identical). Paralogues in human: ENTPD6 (48% identical), ENTPD7 (29% identical), ENTPD4 (28% identical), ENTPD8 (27% identical), ENTPD2 (26% identical), ENTPD1 (25% identical), ENTPD3 (25% identical).
Diseases named in the same sentence as ENTPD5 in open-access papers:
ENTPD5 is named in the same sentence as 48 diseases in open-access papers, as found by Europe PMC text mining. Sharing a sentence is not in itself a finding about the gene and the disease. The quoted sentences say what the papers report.
ovarian carcinoma (5 papers, 2016 to 2026). A malignant neoplasm originating from the surface ovarian epithelium. "Therefore, this study explored the role of ENTPD5 in ovarian cancer cells and its underlying mechanisms." (PMID 35668504, 2022). "ENTPD5 is abnormally overexpressed in several types of malignancies, including prostate, liver, lung, and ovarian cancers." (PMID 41685236, 2026). "ENTPD5 expression patterns in ovarian cancer tissues were analyzed by qRT-PCR and immunohistochemistry assay (IHC)." (PMID 35668504, 2022). "In the present study, we characterized a novel ectonucleoside triphosphate diphosphohydrolase in human ovarian cancer known as ENTPD5 whose biological function was poorly declared." (PMID 35668504, 2022). "Based on the results of this study, we recommend further research on the relationship between ENTPD5 and ovarian cancer intercell environment homeostasis, which may be a new promising treatment for human SOC." (PMID 35668504, 2022). "In these ovarian cancer cells, FN-adhesion was dependent on ITGA5/B1, but independent of ENTPD5, suggesting potential tissue- or cell type-specific requirements for ENTPD5 in integrin folding." (PMID 37563605, 2023). "However, the function and molecular mechanism of ENTPD5 in ovarian cancer have not yet been elucidated." (PMID 35668504, 2022).
prostate carcinoma (5 papers, 2014 to 2021). A carcinoma that arises from epithelial cells of the prostate gland. "Previous studies also highlight the importance of ENTPD5 that is associated with tumor formation and cancerous progression of prostate cancer cell lines." (PMID 25794010, 2015). "Since previous work related ENTPD5 levels to prostate cancer survival, compounds 1a, 1b (as control), and 2f were assayed with prostate cancer cell line LNCaP to determine their effect on cell proliferation." (PMID 31242188, 2019). "The important role ENTPD5 plays in prostate cancer proliferation is consistent with this enzyme being highly expressed in prostate cancer compared to normal prostate epithelium." (PMID 31242188, 2019). "In prostate cancer cells, the enzyme ENTPD5 plays a key role in maintaining the metabolite pool required for glycosylation." (PMID 31242188, 2019). "Existing evidence confirms that ENTPD5 participates in multiple cellular functional processes and promotes the invasion ability of prostate cancer cells with the help of protein kinase Cδ." (PMID 25794010, 2015). "Thus, an inhibitor of ENTPD5 would provide an innovative strategy to target the metabolic machinery that supports cancer growth instead of targeting a prostate cancer driver." (PMID 31242188, 2019). "Compound 1a was also assayed in an additional prostate cancer line, DU145, to investigate the effect of ENTPD5 inhibition on cell lines with differing modes of ENTPD5 overexpression." (PMID 31242188, 2019). "ENTPD5 expression and AKT activation is common in both cultured prostate cancer cell lines and primary human prostate carcinoma." (PMID 25250324, 2014). "Interestingly, evaluation of clinical prostate cancer datasets at the cBioPortal for Cancer Genomics showed that ENTPD5 is infrequently amplified (~ 3%) in a subset of CRPCs 66,67, which suggest ENTPD5 overexpression may have some role in the progression of late-stage PCa." (PMID 34782677, 2021). "Importantly, ENTPD5 is not a prostate cancer driver, but rather ENTPD5 has been shown to be required for supporting prostate cancer growth." (PMID 31242188, 2019).
colorectal cancer (4 papers, 2013 to 2023). A primary or metastatic malignant neoplasm that affects the colon or rectum. "Ectonucleoside triphosphate diphosphohydrolase 5 (ENTPD5) and BCL2 are proto-oncogenes, the former showing lower expression in colorectal cancer than in normal mucosa, while BCL2 is known to inhibit apoptosis and probably plays a role is the early phases of the adenocarcinoma development." (PMID 36765865, 2023). "To investigate the opposite behavior of the miRNA and its target gene, we performed qRT-PCR to measure miR-182 and ENTPD5 expression in a panel of five cell lines (CG-705, HT29, from a primary colorectal tumor, and MICOL-S, MICOL-14, and LoVo, from colorectal carcinoma metastases)." (PMID 23987127, 2013).
breast carcinoma (3 papers, 2015 to 2023). "Some researchers show that overexpression of ENTPD5 affects the growth of many tumors, such as gliomablastoma, breast cancer, cervical cancer, testicular germ cell tumor, and laryngeal neoplasia." (PMID 25794010, 2015).
COVID-19 (3 papers, 2021 to 2022). A disease caused by infection with severe acute respiratory syndrome coronavirus 2. "The multi-trait colocalization analysis suggested robust colocalization evidence to support shared genetic aetiology of the three traits (shared probability=95.4%), which further strengthens the evidence level of the association between ENTPD5 and COVID-19 severity." (PMID 35772218, 2022). "We observed strong MR (P = 5.66 × 10−5) and colocalization (PP=99.9%) evidence to support the effect of gene expression level of ENTPD5 on COVID-19 severity." (PMID 35772218, 2022). "Two examples of this include the proteins ectonucleoside triphosphate diphosphohydrolase 5 (ENTPD5) and tubulointerstitial nephritis antigen like 1 (TINAGL1), which have both been associated with COVID-19 severity." (PMID 34844191, 2021). "MR and colocalization prioritized four protein targets, FCRL3, ICAM5, ENTPD5 and OAS1 that showed effect on COVID-19 severity in European ancestry." (PMID 35772218, 2022). "Herein, we detected the gene expression of ENPP1, ENPP2, ENPP3, ENTPD1 (CD39), ENTPD5, and NT5E (CD73) in the whole blood of COVID-19 patients." (PMID 36248842, 2022). "In addition, our study identified four additional protein targets, FCRL3, ICAM5, ENTPD5 and OAS1, that showed effect on COVID-19 severity in Europeans." (PMID 35772218, 2022).
hepatopathy (3 papers, 2009 to 2024). "It has also been found that ENTPD5 deficient mice develop progressive Hepatopathy, Hepatocellular tumors and spermatogenic arrest." (PMID 36720768, 2023). "Entpd5 knock-out mice are viable but develop progressive hepatopathy, hepatocellular tumors, and spermatogenic arrest; however, no skeletal alteration has been reported." (PMID 39334831, 2024).
Hyperglycemia (3 papers, 2023 to 2025). An increased concentration of glucose in the blood. "Hyperglycemia promotes glucose use in the HBP, thus increasing the level of the end-product UDP-GlcNAc via the rate-limiting enzyme GFAT and increasing the rate of SP1 glycosylation with O-GlcNAc to promote SP1-induced transcription of ENTPD5." (PMID 36849424, 2023). "In hyperglycemia and DKD conditions, the continual increase in UDP-GlcNAc inhibits GFAT expression via a negative feedback mechanism, resulting in a decrease in UDP-GlcNAc levels, inhibiting SP1 modification with O-GlcNAc and, therefore, downregulating ENTPD5 expression." (PMID 36849424, 2023).
metastatic disease (3 papers, 2022 to 2025). "We found seven DEGs (CCND1, EGFR, ENTPD5, HOXA10, IGF1R, MYC, and SNAI2) related to metastatic disease." (PMID 35806108, 2022).
glioblastoma (2 papers, 2019). The most malignant astrocytic tumor (WHO grade IV). "We showed that glioblastoma cells with high p-AKT1/ENTPD5 levels produced SPARC in response to acute RhoA activation." (PMID 31062076, 2019). "The superior invasive capability of glioblastoma cells with high p-AKT1/ENTPD5 levels was limited when AKT1 was blocked." (PMID 31062076, 2019). "Together with the in vitro data, our UM invasion analysis demonstrated that increased AKT-driven ENTPD5 expression enabled glioblastoma cells to produce the Nogo-A decoy SPARC, which was key for their ability to invade the extensively myelinated corpus callosum." (PMID 31062076, 2019). "In contrast, glioblastoma cells with low p-AKT1 levels had low ENTPD5 levels, which could be increased by overexpressing AKT1." (PMID 31062076, 2019). "Since AKT signaling is often upregulated in gliomas due to genetic alterations of PI3 K or PTEN, we investigated whether AKT1-driven ENTPD5 expression is required for glioblastoma cells to produce SPARC." (PMID 31062076, 2019). "Similarly, glioblastoma cells with low p-AKT1/ENTPD5, and thus low endogenous SPARC production, showed increased invasion through myelinated transwells in the presence of recombinant SPARC but not SPARC (del_Kazal)." (PMID 31062076, 2019). "In comparison, the white-matter invasion of glioblastoma cells with low p-AKT1/ENTPD5 levels, such as LNT229 cells, was restricted but could be improved by silencing PTEN (shPTEN)." (PMID 31062076, 2019). "However, not all PTEN-positive glioblastoma cells had low p-AKT1/ENTPD5 levels, whereas WT PTEN-expression in LNT229 glioblastoma cells was responsible for their low p-AKT1/ENTPD5 levels; LN18 cells retained high p-AKT1/ENTPD5 levels even in the presence of WT PTEN [Suppl." (PMID 31062076, 2019). "Ectonucleoside Triphosphate Diphosphohydrolase 5 (ENTPD5) has been shown to be important in maintaining cellular function in cancer, and its expression is upregulated through multiple, unique pathways in certain cancers, including laryngeal, glioblastoma multiforme, breast, testicular, and prostate." (PMID 31242188, 2019). "Thus, the molecular mechanism we discovered may apply to both IDH-wildtype and IDH-mutant glioblastomas, influencing SPARC production via either IRE1α or AKT/ENTPD5 might represent a worthwhile therapeutic option to pursue." (PMID 31062076, 2019).
lung carcinoma (2 papers, 2015 to 2019). "Considering the deficiency of ENTPD5 research in lung cancer and the important role of ENTPD 5 in the process of tumor development, we designed this study to understand the detailed role of ENTPD5 in lung cancer cell growth and invasion process." (PMID 25794010, 2015). "In recent prostate and lung cancer studies, the ectonucleoside triphosphate diphosphohydrolase 5 (ENTPD5) was discovered as being transcriptionally upregulated by activated AKT signaling." (PMID 31062076, 2019). "This study is to investigate the relationship between ectonucleoside triphosphate diphosphohydrolase 5 (ENTPD5) expression and lung cancer clinicopathological factors, and the impact of ENTPD5 on lung cancer cell functions." (PMID 25794010, 2015). "To test the effect of ENTPD5 on lung cancer cell growth and apoptosis in vitro, we successfully constructed the transient transfection cell models." (PMID 25794010, 2015). "To understand the mechanisms of action of proteins related to lung cancer cell apoptosis after the knockdown of ENTPD5, we performed gene chip analysis on PC9 and A549 cells, which was mainly focused on the tests of cell apoptosis pathway." (PMID 25794010, 2015). "In this study, immunohistochemistry analysis confirmed the specific overexpression of ENTPD5 protein in lung cancer tissues." (PMID 25794010, 2015). "Our results suggest that ENTPD5 affects lung cancer apoptosis via Caspase 3 pathway, and can be potentially used to monitor prognosis or to guide appropriate therapeutic regimens." (PMID 25794010, 2015). "Evaluation of ENTPD5 expression levels in different lung cancer lines, including H1975, H1650, H1299, A549, GLC82, PC9 and SKMES1, showed that SKMES-1 had the highest relative ENTPD5 expression." (PMID 25794010, 2015). "This study confirms that ENTPD5 might be related to the occurrence of lung cancer in animal experiments." (PMID 25794010, 2015). "Furthermore, cell growth assay on PC9 and A549 cells with moderate expression of ENTPD5 showed that knockdown of ENTPD5 significantly reduced the growth of lung cancer cells (P < 0.001)." (PMID 25794010, 2015). "Thus, gliomas utilize an AKT/ENTPD5-mediated metabolic shift, similar to prostate and lung cancers." (PMID 31062076, 2019). "In addition, we would like to determine whether ENTPD5 is a promising target in the therapy for lung cancer." (PMID 25794010, 2015). "There are a lot of reports on the relationship between ENTPD5 and malignant tumor growth, but there is almost no report about the correlation between ENTPD5 and lung cancer." (PMID 25794010, 2015).
bladder-cancer (1 paper, 2022).
chronic iridocyclitis (1 paper, 2024). "Two proteins, AIF1 (OR = 0.52; 95% CI 0.40–0.67; P = 5.35 × 10–7) and ENTPD5 (OR = 0.79; 95% CI 0.71–0.89; P = 2.56 × 10–5), were causally associated with chronic iridocyclitis." (PMID 38475831, 2024).
chronic kidney disease (1 paper, 2023). Impairment of the renal function secondary to chronic kidney damage persisting for three or more months. "Because ENTPD5 is pathophysiologically related to renal tubule injury, this work provides a new therapeutic strategy to mediate ENTPD5 expression to protect the kidney against injury in DKD or other forms of chronic kidney disease." (PMID 36849424, 2023).
glioma (1 paper, 2019). A benign or malignant brain and spinal cord tumor that arises from glial cells (astrocytes, oligodendrocytes, ependymal cells). "To assess the clinical potential of our molecular findings, we first focused on glioma cell lines with high p-AKT1/ENTPD5 levels and investigated if a reduction in white matter invasion upon SPARC depletion improves survival in a pre-clinical setting." (PMID 31062076, 2019). "Upon quantifying the invasion along myelinated nerve fiber projections, we found that glioma cells with high levels of p-AKT1 and ENTPD5 were superior at invading white matter due to an increased protein folding capacity." (PMID 31062076, 2019).
kidney failure (1 paper, 2023). An acute or chronic condition that is characterized by the inability of the kidneys to adequately filter the blood. "Herein, we present data demonstrating that ENTPD5 overexpression effectively alleviates kidney failure and in contrast, that ENTPD5 downregulation exacerbates kidney failure." (PMID 36849424, 2023).
liver cancer (1 paper, 2019). An epithelial or non-epithelial malignant neoplasm that arises from the liver. "Research has found that ENTPDs were also associated with cancer, as ENTPD5 affected the proliferation of liver cancer cells." (PMID 31443651, 2019).
melanoma (1 paper, 2023). A malignant, usually aggressive tumor composed of atypical, neoplastic melanocytes. "Altogether, our data indicate that PTEN phosphatase activity inhibits metastasis by negatively regulating the Entpd5/IGF1R pathway through ATF6, thereby identifying novel candidate therapeutic targets for the treatment of PTEN mutant melanoma." (PMID 36824269, 2023). "Knowledge of the status of the PTEN/ATF6/Entpd5/IGF1R axis may prove to be valuable in the design of novel preventive and interventive therapeutic strategies in melanoma." (PMID 36824269, 2023). "We also examined the ATF6 expression in human melanoma by immunohistochemistry using serial tissue microarray sections compared with PTEN, Entpd5 and IGF1R, and found that the ATF6 expression negatively correlated with PTEN expression, while positively with Entpd5 and IGF1R." (PMID 36824269, 2023). "We here show that ATF6 could directly bind to the Entpd5 gene promoter and regulate its expression, linking the UPR signaling-folding protein promoter Entpd5 to cell survival and metastasis of melanoma cells." (PMID 36824269, 2023). "To further understand the biological connection between PTEN and Entpd5/IGF1R pathway, we first assessed the expression levels of ATF6 in melanoma cells carrying the various PTEN mutants by western blot; ATF6 expression was reduced in PTEN WT cells, but enhanced in PTEN ΔLP cells." (PMID 36824269, 2023). "Notably, we demonstrate that PTEN phosphatase negatively regulates the protein N-glycosylation and folding promoter Entpd5 and the Entpd5/IGF1R pathway through Atf6 transcriptional regulation, identifying an important new mechanism by which PTEN inhibits melanoma metastasis." (PMID 36824269, 2023).
minimal change disease (1 paper, 2023). "We studied other proteinuric nephropathies and found that the protein and transcriptional expression of ENTPD5 was increased in minimal glomerular lesions (minimal change disease, MCD) but was decreased in sclerosing glomerulonephritis (SGN)." (PMID 36849424, 2023).